FN1 (fibronectin 1)
Diseases named in the same sentence as FN1 in open-access papers (continued):
Sharing a sentence is not in itself a finding about the gene and the disease.
cervical cancer (24 papers, 2014 to 2026). A primary or metastatic malignant neoplasm involving the cervix. "FN1 has been found to be highly expressed in esophageal and cervical cancers and associated with their prognosis." (PMID 32337286, 2020). "Nonetheless, there are reports that FN1 mRNA expression is significantly higher in cervical cancer compared to normal cervical tissue." (PMID 40141137, 2025). "This regulation was associated with multiple pathways, with overexpression of FN1 significantly rescuing the inhibition of CESC cell proliferation caused by CCT3 knockdown, suggesting that CCT3 upregulation promotes cervical cancer progression through FN1." (PMID 39928781, 2025). "The GEPIA2 database indicates that these oncogenes exhibit upregulation at the mRNA level in cervical cancer, except for FN1." (PMID 40141137, 2025). "Further investigation revealed that CT45A1 markedly elevated both FN1 mRNA and protein levels in cervical cancer cells." (PMID 37924456, 2024). "In particular, the expression level of tumorigenic FN1 was increased 14-fold in cervical cancer Caski cells with CT45A1 expression compared to control cells without CT45A1 expression." (PMID 37924456, 2024). "From the hub gene analysis, FN1 was selected as the most significant hub gene in genistein’s action against the cervical cancer network." (PMID 36838908, 2023). "FN1 encodes fibronectin, which monitors proliferation and metastasis by regulating the FAK signaling pathway in cervical cancer cells." (PMID 36838908, 2023). "The results of pairwise gene correlation analysis of GEPIA2 data showed that the expression of FN1 was positively related to ITGA5 expression in cervical cancer." (PMID 36999964, 2023). "They found significantly higher FN1 levels in cervical cancer tissues than in adjacent normal tissues." (PMID 36101337, 2022). "The correlation between HK2 and Akt1, p-Akt1, FN1 expression in cervical cancer cells and human squamous cervical carcinoma (SCC) samples was verified in this study." (PMID 34758823, 2021). "In cervical cancer, aberrant FN1 expression was confirmed to be involved in cell viability, apoptosis, migration and invasion." (PMID 34758823, 2021). "As shown in this study, exogenous expression of HK2 activated Akt1 (p-Akt1) in cervical cancer cells, subsequently enhancing cell motility and tumor metastasis by inducing FN1, MMP2 and MMP9 expression." (PMID 34758823, 2021). "Together, these data suggest that CT45A1 regulates FN1 gene transcription in cervical cancer cells." (PMID 37924456, 2024). "We detected the FN1 expression in cervical cancer cells and cells cultured with FN1 substrate by immunofluorescence staining and qRT‐PCR, which showed that cervical cancer cells can secrete FN1 by themselves and a significant upregulation of FN1 expression in FN1 coated cells." (PMID 36999964, 2023). "This study demonstrated that HK2 could activate Akt1 in cervical cancer cells, subsequently enhancing cell motility and tumor metastasis by inducing FN1, MMP2 and MMP9 expression." (PMID 34758823, 2021). "In conclusion, this study demonstrated that HK2 could activate Akt1 (p-Akt1) in cervical cancer cells, subsequently enhancing cell motility and tumor metastasis by inducing FN1, MMP2, and MMP9 expression." (PMID 34758823, 2021). "However, the molecular mechanism of interaction between HK2 and FN1 in cervical cancer remains unknown." (PMID 34758823, 2021). "The upregulated ligand receptor pairs in the cervical cancer group were SPP1 − CD44, FN1 − SDC4, FN1 − SDC1, FN1 − CD44, CD99 − CD99, and the downregulated ligand receptor pairs were PPIA – BSG, LGALS9 − P4HB, LGALS9 − CD44." (PMID 41384115, 2025). "Both FN1 and PLAU play pivotal roles in extracellular matrix degradation, facilitating the migration and invasion of cervical cancer cells." (PMID 40141137, 2025).
cervical cancer (continued). "Overexpression and/or activation of tumorigenic signaling proteins, including FN1, SRC, CREB, YAP, and TAZ, play a critical role in the progression of cervical cancer." (PMID 37924456, 2024). "We found that decreased FN1 expression inhibited the phosphorylation of AKT and the expression of VEGFA in cervical cancer cells." (PMID 36999964, 2023). "For example, the core proteins such as FN1 and APOF were involved in the process of cervical cancer." (PMID 36498728, 2022). "Further studies demonstrated that this promotion of cell motility by HK2 was probably a result of it inducing FN1, MMP2 and MMP9 expression by activating Akt1 in cervical cancer cells." (PMID 34758823, 2021). "All of these results demonstrate that stimulated HK2 expression induces Akt1 (p-Akt1), FN1, MMP2 and MMP9 expression in cervical cancer cells." (PMID 34758823, 2021). "All of these results further confirm that HK2 induces FN1, MMP2, and MMP9 expression by stimulating Akt1 (p-Akt1) in cervical cancer cells, subsequently enhancing cell motility." (PMID 34758823, 2021). "Notably, immunohistochemistry and western blot assays confirmed that FN1, PLAU, and ICAM1 are significantly upregulated in cervical cancer tissues." (PMID 40141137, 2025). "Moreover, to further verify the influence of FN1 on AKT pathway and the expression of VEGFA in cervical cancer cells, we performed Western Blotting to evaluate the expression of AKT, p‐AKT, and VEGFA in the tumor cells transfected with siFN1 or siNC." (PMID 36999964, 2023). "FN1 upregulation has been reported to activate MMP2 and MMP9 via the FAK and PI3K/Akt pathways, promoting tumor metastasis in lung, gastric, breast, ovarian and cervical cancer." (PMID 36151071, 2022). "Therefore, we supposed that such stimulation of FN1 in HK2-overexpressing cells was probably responsible for the promoting effect of HK2 on cell motility and tumor metastasis in cervical cancer." (PMID 34758823, 2021). "To verify whether FN1 could promote ITGA5‐mediated angiogenesis in vitro, we downregulated FN1 in cervical cancer cells transfected with siRNAs (siFN1 vs. siNC) or cultured cells in FN1‐containing substrate (+fibronectin vs. control) to manipulate the FN1‐ITGA5 interaction." (PMID 36999964, 2023).
Myocardial fibrosis (23 papers, 2012 to 2026). "The composition of the ECM includes fibronectin, and FN1 expression in fibroblasts is increased in the presence of myocardial fibrosis and myocardial failure." (PMID 40785031, 2025). "We found that tRF-Glu-CTC-013 reduced the expression of Tgfb1, Col1a1, Col3a1 and Fn1, thereby inhibiting myocardial fibrosis." (PMID 40520901, 2025). "Meanwhile, the FN1 pathway is well-established to exert significant effects on myocardial fibrosis, aiding the determination of dilated cardiomyopathy etiology and providing a potential therapeutic target." (PMID 35401927, 2022). "FN1 has been identified to play an important role in myocardial fibrosis, contributing to identifying the etiology of dilated cardiomyopathy." (PMID 35401927, 2022). "Furthermore, Fn1 polymerization is needed for collagen sediment and plays a vital position in myocardial ischemia/reperfusion injury-induced inflammation, myocardial fibrosis, and neovascular formation after infarction." (PMID 40271502, 2025). "Actually, FN1 has been used as a myocardial fibrosis marker in research." (PMID 36398072, 2022). "More recently, an integrated analysis of hub genes and miRNAs using data of DCM patients from the GEO database (GSE112556) identified miR-144-3p and miR-9-3p as potential regulators of myocardial fibrosis in DCM that target the fibronectin 1 (FN1) gene, an extracellular matrix component." (PMID 36362356, 2022). "As the target gene of miR-144 and miR-9, it can be concluded that the miR-144/FN1 and miR-9-3p/FN1 might be necessary in the progresses of myocardial fibrosis in DCM." (PMID 33015184, 2020). "In this study, we constructed the miRNA-mRNA network in DCM pathogenesis and identified that the miR-144-3p/FN1 and miR-9-3p/FN1 pathways could be involved in the pathogenesis of myocardial fibrosis in DCM, providing potential therapeutic targets in DCM disease." (PMID 33015184, 2020). "The study uncovered several important hub genes and miRNAs involved in the pathogenesis of DCM, among which, the miR-144-3p/FN1 and miR-9-3p/FN1 pathways may play an important role in myocardial fibrosis, which can help identify the etiology of DCM, and provide potential therapeutic targets." (PMID 33015184, 2020). "Immunofluorescence results showed that macrophages treated with high glucose exhibited an increased expression of α-SMA and fibronectin-1 (FN-1) in H9C2 cells, contributing to myocardial fibrosis." (PMID 40003929, 2025). "Consistently, Masson’s trichrome staining demonstrated a significant reduction in myocardial fibrosis after RDN, with lower expression of fibrosis-related genes including Col1a2, Timp1, Fn1 and α-SMA." (PMID 40958035, 2025). "The expression of myocardial fibrosis markers COL1, COL3 and FN1 was detected by immunohistochemistry to investigate the ameliorative effect of canagliflozin on myocardial fibrosis." (PMID 40785031, 2025). "The decline in cardiac function in HFpEF mice was also accompanied by a significant increase in the mRNA expression levels of Bnp and genes related to myocardial fibrosis, such as α-SMA, Fn1, Col1a2, and Timp1." (PMID 38402404, 2024). "Histological analyses revealed increased myocardial fibrosis in Musclin KO mice in response to TAC compared to WT mice, which was accompanied by upregulation of pro-fibrotic genes like Postn, Col1a1, Col3a1 and Fn1." (PMID 35013221, 2022). "As collagen deposition in the extracellular matrix is a key factor in the development of myocardial fibrosis, and fibronectin 1 (FN1) is involved in the promotion of collagen secretion by fibroblasts, we proceeded to investigate the expression of collagen I, collagen III and FN1." (PMID 37313693, 2023). "Moreover, there was a non-significant increase in myocardial fibrosis, measured by staining histological sections with Masson’s trichrome, and a significant increase in LV expression of a fibrosis-related gene, fibronectin-1." (PMID 25915632, 2015).
Hyperglycemia (22 papers, 2011 to 2025). An increased concentration of glucose in the blood. "Db/db mice with pressure ulcers showed an impairment in the molecular regulation of hypoxia-related genes (Hif1a, Flt1, and Kdr), while extracellular matrix encoding genes (Itgb3, Timp1, Fn1, Col4a1) were upregulated by hyperglycemia and lesions." (PMID 35386010, 2022). "FN1 is an accumulation constituent of the ECM in the case of hyperglycemia." (PMID 38903804, 2024). "One of the more important findings of this work was that PVT1 effects on expression of FN1, COL4A1, and PAI-1 may be mediated independently of TGFB1, a well-known profibrotic factor which promotes tissue fibrosis by upregulating genes encoding ECM proteins in response to hyperglycemia." (PMID 21526116, 2011). "Interestingly, aside from its protective role in hyperglycemia, circRNA_012164 knockdown had no significant impact on basal levels of any genes, except for Fn1." (PMID 39042659, 2024).
keloid (22 papers, 2013 to 2025). An irregularly shaped, elevated mark on the skin caused by deposits of excessive amounts of collagen during wound healing. "Overproduction of ECM, including fibronectin-1 and thrombospondin-1, is a hallmark of keloid fibroblasts." (PMID 41465196, 2025). "In fibrotic conditions, such as keloids, fibronectin-1 is often overexpressed and contributes to the excessive deposition of ECM components, primarily collagen." (PMID 41465196, 2025). "In keloids, knockdown of fibronectin-1 has been shown to inhibit TGFB1-mediated cell proliferation and collagen deposition via AKT/ERK signalling pathway." (PMID 41465196, 2025). "Our immunostaining results also indicated that TEM1 expression was significantly higher in hypertrophic scars and keloids than in normal skin, as well as being associated with fibroblast activation markers such as α-SMA, COL1A1, and FN1." (PMID 38254097, 2024). "The transcriptomic levels of TEM1, as well as of COL1A1 and FN1, were predominantly upregulated in the Fs1 subgroup which comprised almost half of all keloid fibroblasts." (PMID 38254097, 2024). "Inhibiting IL-6 or IL-6 receptor α (IL-6Rα) in keloid fibroblasts revealed a dose-dependent decrease in collagen type I α 2 and fibronectin 1 mRNAs." (PMID 37895153, 2023). "Unexpectedly, in the discovery datasets, the expression of FN1 was significantly upregulated in keloid but significantly downregulated in the GSE113619 dataset." (PMID 35872873, 2022). "First, the Western blotting results of keloids and the adjacent normal skin from the same subjects revealed that the expression levels of STAT3, COL1A1, and FN1 were increased in keloids relative to those in normal skin." (PMID 35628356, 2022). "In the current study, PTB suppression also caused the reduction of FN1 expression in transplanted keloid tissues and TGF-β1-treated keloid fibroblasts." (PMID 27897224, 2016). "The expression of FN1 increased significantly after 24 hours of TGF-β1 treatment in keloid fibroblasts, which was earlier than in normal fibroblasts." (PMID 27897224, 2016). "Direct targeting of FN1 in pro-fibrotic keloid fibroblasts (kFB) may provide additional insight into the central role of FN1 in mediating BioD’s anti-fibrosis response." (PMID 41465196, 2025). "In addition to normal fibroblasts, we investigated the effect of BioD on the expression of fibronectin-1 and thrombospondin-1 in keloid-derived fibroblasts (kFB)." (PMID 41465196, 2025). "Furthermore, suppressing PTB has been shown to decrease the expression of fibronectin 1 (FN1) in transplanted keloid tissues and TGF-β1-treated keloid fibroblasts." (PMID 37875914, 2023). "The results may explain the lower cell density and ECM accumulation in the PTB siRNA group, and suggest that PTB regulates cell proliferation and transcription of COL3A1 and FN1 in vivo in keloid tissues." (PMID 27897224, 2016). "Notably, FTY720 decreased α-SMA, CTGF, and FN1 protein levels in keloid skin fibroblasts." (PMID 32505218, 2020). "Although CDH1 gene expression levels are similar between normal and keloid keratinocytes, keloids express decreased protein levels of E-cadherin, in line with cadherin switching from E-cadherin to mesenchymal markers such as N-cadherin, fibronectin-1, vimentin, and cadherin-11." (PMID 31440236, 2019). "Multi-omics investigations, including proteomics, have identified abundant levels of collagens (I and III), FN1, THBS1, and TGFB1 in keloids compared to normal skin." (PMID 41465196, 2025). "RSL3 injection into keloid tissue dramatically decreased the mRNA levels of fibrotic genes, such as α-SMA, COL1A1, COL1A2, COL3A1, and FN1, and downregulated the ECM contents, according to qPCR analysis and the Sircol test." (PMID 40860189, 2025). "In keloid tissues, TEM1 was found to co-localize with several fibroblast-activated markers, including α-SMA, COL1A1, and FN1, supporting its expression in fibroblasts within the scar tissue." (PMID 38254097, 2024).
keloid (continued). "ScRNA-seq analysis identified consistent expression patterns for TEM1, ACTA2, COL1A1, FN1, TGFBR1, and TGFBR2 in distinct fibroblast subsets of both keloids and hypertrophic scars." (PMID 38254097, 2024). "We demonstrated, in scRNA-seq datasets of hypertrophic scars and keloids, that the TEM1 gene was mostly co-expressed with the COL1A1 and FN1 genes in a specific and major sub-population of fibroblasts." (PMID 38254097, 2024). "Expression of extracellular matrix protein FN1 and bone matrix protein OPN was identified in keloids, whereas these proteins were reduced in the PK group." (PMID 37275903, 2023). "Genes involved in extracellular matrix formation including COL1A1, COL3A1, POSTN, COL1A2, FN1, and ASPN were significantly upregulated in keloid compared to the normal skins." (PMID 35990663, 2022). "This study reports that a decellularized ECM scaffold may significantly attenuate pro-fibrotic responses in both normal and keloid fibroblasts via TSP1 and FN1-dependent mechanisms." (PMID 41465196, 2025). "In addition, the mRNA expression levels of ECM genes including COL1A1 and FN1 as well as that of TGF-β-related genes such as TGFB1, TGFBR1, and TGFBR2 were highly expressed in keloids." (PMID 38254097, 2024). "The fact that we observed the upregulation of FBLN1, FN1, and PDGFRL in keloids in our proteomic profiles enhances the possibility of this hypothesis." (PMID 35435317, 2022). "In the PTB siRNA group, the expressions of COL3A1 and FN1 but not COL1A1 significantly decreased in keloid xenograft tissues." (PMID 27897224, 2016). "Moreover, when PTB was suppressed, there was a reduction in excessive deposition of FN1 and COL3A1 in transplanted keloid tissues." (PMID 27897224, 2016).
head and neck squamous cell carcinoma (21 papers, 2017 to 2025). A squamous cell carcinoma that arises from any of the following anatomic sites: lip and oral cavity, nasal cavity, paranasal sinuses, pharynx, larynx, and salivary glands. "Furthermore, FN1 is a biomarker for head and neck squamous cell carcinoma due to its strong association with epithelial–mesenchymal transition and tumor invasion/metastasis." (PMID 35614192, 2022). "Fibronectin 1 (FN1) is significantly overexpressed in head and neck squamous cell carcinoma (HNSCC) and correlates with higher pathologic stages and a poor prognosis." (PMID 39518152, 2024). "FN1 is involved in tumor occurrence and development and is upregulated in various cancers, such as head and neck squamous cell carcinoma and cadmium-related bladder cancer." (PMID 37328752, 2023). "The results showed that the mRNA and protein expression of GSK3B, PIK3CA, FN1, MET, and SPP1 was significantly upregulated in head and neck squamous cell carcinoma tissues, while MAPK3 was significantly downregulated." (PMID 39323640, 2024). "In the context of head and neck squamous cell carcinoma (HNSCC), Liu found that p62 regulates the degradation of FN1 through a p62-dependent autophagy-lysosome pathway." (PMID 38365674, 2024). "However, the role of FN1 in the diagnosis and prognosis of head and neck squamous cell carcinoma (HNSCC) is far from understood." (PMID 34746236, 2021).